IL6 (interleukin 6)
Diseases named in the same sentence as IL6 in open-access papers (continued):
Sharing a sentence is not in itself a finding about the gene and the disease.
AIDS (continued). "Consistent with this specific effect, no changes in raltegravir-intensified patients were observed for other inflammatory markers such as IL-6, whose levels have been recently shown to predict non-AIDS-defining morbid events during suppressive HAART." (PMID 25462535, 2014). "Especially, there are high levels of IL-6 and IL-10 in body cavity effusions from AIDS patients with PEL." (PMID 24587336, 2014). "Higher levels of IL-6, IL-10 and G-CSF were associated with hospital mortality among HIV/AIDS septic patients." (PMID 23874739, 2013). "The IL-6, IL-10 and G-CSF levels were associated with hospital mortality in the HIV/AIDS septic group; however, the CRP levels and the surrogates of innate immune activation (cytokines) were similar among HIV/AIDS and non-HIV septic patients." (PMID 23874739, 2013). "A recent retrospective case-control study in HIV+ patients demonstrated that higher pre-ART plasma levels of IL-6, D-dimer and CRP are associated with increased risk of AIDS events, IRIS or death." (PMID 23691062, 2013). "In our study, three cytokines (IL-6, IL-10 and G-CSF) were associated with hospital mortality in HIV/AIDS septic patients." (PMID 23874739, 2013). "The results demonstrate the multiple mechanisms involved in the interaction between TGF-β and IL-6 signaling in AIDS- or SAIDS-NHL cell lines, and suggest a balance between positive and negative growth regulatory influences in this disease." (PMID 17324269, 2007). "IL-10 has been shown to block HIV-induced TNF-α and IL-6 secretion and inhibit HIV replication, and a cohort study of 51 people with HIV suppressed on ART demonstrated decreasing plasma IL-10/TNF-α ratio to be associated with AIDS progression." (PMID 38019897, 2023). "Thus, IL-6 inhibitors with the ineffectiveness of IL-1 inhibitors can be considered potential methods of treatment for AIDs." (PMID 38034538, 2023). "Overactivated autoreactive immune cells such as T cells, DCs, and macrophages produce pro-inflammatory cytokines, including IL-1β, IL-6, IL-17, IL-23, COX-2, and iNOS, or chemokines that promote the recruitment of inflammation-associated cells in the affected areas of AIDs." (PMID 37006236, 2023). "Similarly to IL6 and IL10, circulating BAFF levels correlate with complete remission rate, overall survival and progression-free survival in AIDS-associated NHL." (PMID 35008292, 2021). "Indeed, circulating markers of intestinal permeability (intestinal fatty acid binding protein [I-FABP] and zonulin) and IL-6 have been consistently predictive of non-AIDS events and mortality in people receiving suppressive ART." (PMID 31139758, 2019). "In the adjusted models concentrations of four markers were significantly inversely associated with AIDS-KS risk including sGP130 (OR=0.14, 95% CI = 0.03–0.73, BAFF (OR=0.60, 95% CI =0.16–0.90), sCRP (OR=0.61, 95% CI = 0.43–0.87) and IL-6 (OR=0.51, 95% CI = 0.35–0.76)." (PMID 33521162, 2018). "According to this theory, immune activation (following an infection such as HIV/AIDS) releases pro-inflammatory cytokines such as interferon gamma (IFNγ), interleukin 6 (IL-6), and tumor necrosis factor alpha (TNF-α) which induce secretion of indoleamine 2, 3-dioxygenase (IDO)." (PMID 29298663, 2018). "Furthermore, inflammatory mediators (e.g., IL-6) secreted by monocytes predict serious non-AIDS events in virologically suppressed HIV-infected subjects." (PMID 28785262, 2017). "Furthermore, although the relationship between IL-6 and IL-10 is unclear in HIV+ subjects, these cytokines appear to be intrinsically linked to infection progression and AIDS onset." (PMID 27214135, 2016). "Plasma IL-8, LDH, and HBDH levels and IL-6/IL-10 ratio could be helpful for early evaluation of the severity and predicting fatal outcomes in AIDS PCP patients." (PMID 27579328, 2016).
AIDS (continued). "A recent study found that monocyte activation and not T-cell activation was strongly associated with markers of systemic inflammation and coagulation (IL-6, hsCRP and D-dimers) which has been shown to predict many serious non-AIDS events (SNAEs) and mortality in HIV-infected individuals." (PMID 25622527, 2015). "Conversely, our data suggests that miRs could indirectly act on key regulators of STAT3/IL-6 axis ultimately contributing to the chronic immune activation observed in AIDS." (PMID 26116514, 2015). "Therefore, this approach allowed us to identify important differences involving IP-10, TNF-α, IL-6, IFN-α, and IL-10 interactions that play important roles in AIDS and are a hallmark between the two treatments here analyzed." (PMID 26684789, 2015). "However, in contrast to sCD14, patients with high and low levels of IL-6 differed in their rate of progression to AIDS during clinical follow-up." (PMID 21526194, 2011). "In contrast, we found a positive correlation between IL-6 and anti-CBir1 in AIDS patients." (PMID 21125014, 2010). "The secretion of IL-6 is further significant in AIDS-NHL because it may render the tumor cells resistant to the cytotoxic effects of chemotherapeutic drugs and/or increase the side effects." (PMID 17324269, 2007). "An association between low vitamin D levels and increases in markers of inflammation including interleukin-6 (IL-6) and high-sensitivity C-reactive protein (hs-CRP) has been reported, while higher vitamin D levels were independently associated with a lower risk of mortality and AIDS events." (PMID 33066266, 2020). "In previous SMART reports, we showed that baseline levels of IL-6, hsCRP and D-dimer were all strongly related to all-cause mortality, and that IL-6 and hsCRP, but not D-dimer, were associated with the development of AIDS events." (PMID 22970224, 2012). "Finally, studies were performed to determine whether IL-6 acts on human AIDS-NHL cells by STAT3 stimulation as it does in LCL8664." (PMID 17324269, 2007). "Analysis of three human AIDS-NHL-derived cell lines was undertaken to establish which subtype(s) might be faithfully modeled by the LCL8664 cell line with respect to the response to IL-6 and TGF-β1." (PMID 17324269, 2007). "A recently study reported that IL-6 was higher in AMD patients than in cataract patients, who all also had AIDS." (PMID 35370941, 2022). "Compared to healthy individuals, HIV/AIDS patients with cryptococcal meningoencephalitis displayed higher CSF levels of IFN-γ, TNF-α, IL-6, IL-7, IL-8, IL-10, IL-12p40, IL-15, IL-18, and CCL2." (PMID 36557672, 2022). "In the clinic, some cytokines induced by TLRs are immunotherapeutic targets in AIDs, such as TNF-α, interleukin (IL)-6, interferon (IFN)-α, and IL-1β." (PMID 35126357, 2021). "Elevation of TNF-α, IL-6, and downregulation of IFN-γ, as already reported in AIDS patients, marked upregulation of miRNA 125b-5p." (PMID 32126572, 2020). "It is interesting to note that intestinal tissue samples in that prior study included 10 gut biopsies from CMV-infected AIDS participants, and CMV-specific antigens were detected in all 10 samples, 4 of which were double-positive for both CMV and IL-6." (PMID 28241080, 2017). "In contrast, IL6 and TNFA were each increased in Pt-1 and Pt-2, respectively, while IL1B expression was increased in both HIV/AIDS patients’ brains compared to uninfected controls." (PMID 29037245, 2017). "Among downstream genes, two specific metalloproteases, ADAMTS1 and 9, are strongly expressed in AIDS-KS tissues and contribute to KSHV-infected endothelial cell invasiveness through up-regulation of IL-6 and VEGF." (PMID 26675551, 2016). "The IL-6 & D-dimer score could be a suitable biomarker outcome in phase II trials to compare drugs with different mechanisms of action (targeting inflammation, coagulation, or both) for their estimated, model-predicted potential to reduce non-AIDS morbidity and mortality." (PMID 27171281, 2016).
AIDS (continued). "Additional markers of innate immune activation, including interleukin-6 [IL-6] and the acute phase molecule C-reactive protein [CRP], are also predictive of non-AIDS HIV mortality." (PMID 26204934, 2015). "A mechanism mediated by pro-inflammatory cytokines, such as IL6 and IL-8, would contribute to immune dysregulation seen in HIV-1 infected patients and, hence, promoting HIV-1 viral replication and progression to AIDS." (PMID 26090662, 2015). "LPS stimulation of total MMC from AIDS patients induced a further increase in TNF-α (median: 17.9 vs 31.8 pg/mL in unstimulated vs. stimulated MMC, respectively, p = 0.031) and IL-6 (median: 19.3 vs 45.46 pg/mL, respectively, p = 0.006) secretion." (PMID 26475133, 2015). "Markers of monocyte activation (sCD14 and IL-6) have been considered as powerful predictive parameters of evolution of HIV-infection, due to both AIDS- and non-AIDS related entities, and they have been proposed in risk stratification strategies." (PMID 25775475, 2015). "Ex vivo studies of total MMC (containing CD14+ macrophages) isolated from the colon of AIDS patients indicated that these cells secreted increased levels of TNF-α, IL-6, CCL2 and CXCL10 compared to HIV-negative controls." (PMID 26475133, 2015). "IL-6, IL-10 and G-CSF are biomarkers that can be used to predict prognosis and outcomes in HIV/AIDS septic patients." (PMID 23874739, 2013). "Together with previous studies demonstrating that CBir1 antigen can induce IL-6 and other proinflammatory cytokines, this finding raises the possibility that translocation of flagellin into the circulation may be a factor that contributes to immune activation in AIDS." (PMID 21125014, 2010). "By comparison, human AIDS-NHL cell lines were observed to vary in their responsiveness to TGF-β1 and to IL-6." (PMID 17324269, 2007). "IL-6 is a stimulator of B-cell proliferation and differentiation that is expressed in EBV-positive AIDS-BL and to high levels in AIDS-DLBCL of both centroblastic and immunoblastic types." (PMID 17324269, 2007). "The present study was designed to examine the negative and positive growth regulatory influences of TGF-β1 and IL-6, respectively, on SAIDS- and AIDS-NHL cells." (PMID 17324269, 2007). "Three human AIDS-NHL-derived cell lines representing distinct histologic subtypes, i.e., 2F7, BCBL-1 and UMCL01-101, were treated with IL-6, TGF-β1, or a combination of both cytokines for 0 to 6 days, and growth was measured at regular intervals by MTT assay." (PMID 17324269, 2007). "Increased IL-6 levels have been observed in the serum and plasma of HIV patients even under ART, and IL-6 was considered a stronger predictor of fatal events related to AIDS." (PMID 38675216, 2024). "AIDS progression is strongly correlated with inflammatory markers and chronic immune activation, and upregulated expression of pro-inflammatory cytokines such as TNF and IL-6 has been documented both in vitro and in vivo during HIV-1 infection." (PMID 39459974, 2024). "However, IL-6 was significantly raised in the patient’s serum, as previously observed in different NLRP3-AIDs." (PMID 34671876, 2022). "In fact, a strong correlation between biomarkers impacted by the same condition, namely, IL-6, sCD14, hs-CRP, and D-dimer, has generally been shown in most cohort studies, and all of them were predictors of AIDS, serious non-AIDS events, mortality, and a broad array of morbidities." (PMID 35572577, 2022). "According to the recent study in South Africa, IL-1RA, IL-6, IL-8, MIP-1α, MIP-1β, and IP-10 could segregate deceased patients from survivors in AIDS/TB." (PMID 33143141, 2020). "The inflammatory markers of concern are many but due to the biological and laboratory reproducibility of IL-6 and CRP, and their ability to predict the occurrence of non AIDS events, this study assessed the levels of CRP and IL-6 among PLHIV with dysglycemia in Tanzania." (PMID 31331321, 2019).
AIDS (continued). "Human IL-6 can promote growth of KSHV-infected PEL cell lines and AIDS-KS-derived cells." (PMID 27893764, 2016). "Taken together with our observations, these results suggest a strong association of high IL-6 and IL-10 levels with progression through the stages of HIV infection to AIDS regardless of the patients’ progression group." (PMID 27214135, 2016). "Treatments to decrease IL-6 and D-dimer might substantially reduce morbidity and mortality in HIV-positive patients on suppressive ART, since non-AIDS conditions dominate morbidity in this population." (PMID 27171281, 2016). "Because the IL-6 levels were similar in the HIV/AIDS and non-HIV septic patients, our data suggest that IL-6 can be a predictor of poor outcomes in the HIV/AIDS septic population." (PMID 23874739, 2013). "The HIV/AIDS non-surviving patients presented significantly higher levels of IL-6, IL-10 and G-CSF when compared with the survivors; however, the cytokine levels were similar between the HIV and non-HIV septic patients." (PMID 23874739, 2013). "The IL-6 levels were higher in the non-survivor HIV/AIDS septic patients when compared with the HIV/AIDS survivors." (PMID 23874739, 2013). "Plasma levels of IL-6 and D-dimers (products of fibrinolysis) predict mortality in HIV-1 infection and pretreatment plasma levels of the TNFr1 and IL-6 also predicted AIDS events and death in treated patients." (PMID 24367599, 2013). "Elevated catabolic chemokines such as TNF-α, IL-1, IL-6 and interferon which are thought to be responsible for inflammation induction have been documented in AIDS patients without evidence of any secondary infection." (PMID 24198891, 2013). "We detected higher levels of IL-2R, CXCL9, CXCL10, CCL2, and IL-6 (p = 0.001, 0.0003, 0.0002, 0.017, and 0.0005, respectively) in plasma of AIDS patients compared to healthy uninfected controls (data not shown)." (PMID 21125014, 2010). "Plasma levels of LPS, sCD14, IL-6, and CCL2 were higher in AIDS compared to uninfected subjects." (PMID 18575590, 2008). "Of the five cytokines we studied, only IL-12 appeared not to be elevated in patients with AIDS related diarrhoea, but IL-6 and MIF were not directly related to mortality." (PMID 19014537, 2008). "As LCL8664 and other SAIDS-NHL-derived cell lines are useful to the extent that they faithfully model AIDS-NHL, studies were next performed to establish which subtype(s) of AIDS-NHL is (are) effectively modeled by LCL8664 with respect to their response to IL-6 and TGF-β1." (PMID 17324269, 2007). "Of cell lines examined representing three different AIDS-NHL subtypes, only a recently derived, uncharacterized cell line designated UMCL01-101 demonstrated sensitivity to TGF-β1-mediated inhibition and partial rescue by IL-6." (PMID 17324269, 2007). "The results demonstrated that AIDS-NHL cells are variably sensitive to TGF-β1-mediated growth inhibition and to IL-6 stimulation, an indication that the response to cytokines such as these may be a distinguishing characteristic of tumor cell phenotype." (PMID 17324269, 2007). "Monocytes are chronically activated during HIV infection and it is now evident that inflammatory mediators produced by monocytes (especially IL-6), independent of T cell activation, also predict serious non-AIDS events (SNAEs) in virologically suppressed HIV-infected persons treated with ART." (PMID 31165257, 2019). "In addition, our study evaluated the relationship among the classical markers of AIDS progression, i.e., CD4+ T-cell count, median viral load and cytokine levels, and revealed a correlation between increased viral load and increased IL-6 levels (rho = 0.75, p = 0.02)." (PMID 27214135, 2016). "The IL-6 and IL-8, secreted by both HIV-1 infected and neighboring non-infected cells following stimulation by released extracellular Tat protein, may promote HIV-1 replication and progression to AIDS through several immune mechanisms." (PMID 26090662, 2015).
AIDS (continued). "The over-production of IL-6 and IL-8, in combination with other pro-inflammatory cytokines, may contribute to an increase in HIV-1 viral replication and to a fast progression to AIDS." (PMID 26090662, 2015). "In fact, surrogate biomarkers of chronic inflammation/hypercoagulability, such as IL-6, HsPCR and D-dimer, are altered in HIV-infected subjects compared to matched uninfected controls, and correlate with the frequency of both AIDS and non-AIDS events and also with overall mortality." (PMID 23678991, 2013). "The present study was conducted to assess whether other SAIDS-NHL and AIDS-NHL cell lines are similarly sensitive to the growth inhibitory effects of TGF-beta, and to test the hypothesis that interleukin-6 (IL-6) may represent a counteracting positive influence in their growth regulation." (PMID 17324269, 2007). "Whether IL-6 can rescue B-lymphoid cells from TGF-β1-mediated growth inhibition had not previously been reported, although IL-6 is expressed in AIDS-NHL by the tumor cells themselves or by tumor-infiltrating cells." (PMID 17324269, 2007). "Taken together, these findings indicate that immunoblastic AIDS-DLBCL remains sensitive to TGF-β1-mediated growth inhibition, and that the inhibition may be overeome through the stimulation of proliferative and anti-apoptotic signals by IL-6." (PMID 17324269, 2007). "The present study was conducted to assess whether other SAIDS-NHL and AIDS-NHL cell lines are similarly sensitive to the growth inhibitory effects of TGF-β, and to test the hypothesis that IL-6 may represent a counteracting positive influence in their growth regulation." (PMID 17324269, 2007). "Moreover, the studies indicate that the sensitivity of immunoblastic AIDS-DLBCL to TGF-β1-mediated growth inhibition may be overeome through the stimulation of proliferative and anti-apoptotic signals by IL-6." (PMID 17324269, 2007). "In the absence of LPS, unstimulated total MMC from AIDS patients secreted significantly higher levels of macrophage related pro-inflammatory cytokines (TNF-α and IL-6) and chemokines (CCL2, CXCL10) compared to the MMC isolated from healthy controls." (PMID 26475133, 2015). "Similarly, in an AIDS Malignancy Consortium study on rapamycin with HAART, no significant changes in IL-6 and VEGF plasma concentrations, viral load and CD4 counts were observed during KS monitoring." (PMID 26296972, 2015).